CD4 (CD4 molecule)
Diseases named in the same sentence as CD4 in open-access papers (continued):
Sharing a sentence is not in itself a finding about the gene and the disease.
tumor (continued). "In comparison, extensive recruitment of CD4+ and CD8+ T cells and macrophages was detected in tumor lesions of α-gal(+) PDAC-ly vaccinated KO mice." (PMID 29077749, 2017). "In the present work we also found MAP17-positive tumors surrounded by CD4+ and CD8+ T cells in the tumor microenvironment." (PMID 29228712, 2017). "Tumor-infiltrating lymphocyte markers: CD3, CD4, CD8, CD20 and CD163 were evaluated using RNA-Seq data." (PMID 28537889, 2017). "Overall, the quantitative changes observed in CD4+, CD8+, and Treg T-cell subset composition of TdLN from shCD5EμTg mice would be compatible with a more efficient anti-tumor response." (PMID 29296231, 2017). "IRF-1 functions both as a tumor suppressor and regulator of immune response, and is required for IFNγ-mediated TH1 differentiation in CD4+ T cells." (PMID 28642803, 2017). "Step 2 exposure to exogenous IL-7 or IL-7+IL-2 produced selective and sustained expansion of both CD4+ and CD8+ peptide-specific T-cells with a predominant interferon-?-producing T1-type, as well as the antigen-specific ability to lyse tumor targets." (PMID 27974697, 2017). "The tumor infiltrating CD11b+CCR8+ myeloid subset produced significant amount of proinflammatory IL-6 and angiogenic VEGF and induced the differentiation of CD4+FoxP3+ regulatory T-cells." (PMID 28197019, 2017). "Both CD4+ helper T cells and CD8+ cytotoxic T cells were essential for induction of an anti-tumor immune response as demonstrated by in vivo depletion of these subsets." (PMID 28116088, 2017). "In vitro studies demonstrate that the CD3xPDL1 BiTE simultaneously binds to both CD3 and PDL1, and activates healthy donor CD4+ and CD8+ T cells and NKT cells that are specifically cytotoxic for PDL1+ tumor cells." (PMID 28938530, 2017). "The proportion of CCR2+ cells was around 50% lower among both CD4+ and CD8+ T lymphocytes in tumor as compared with unaffected tissue." (PMID 29020986, 2017). "Nevertheless, it has been shown that 9/10 gastrointestinal cancer patients had CD4+ and/or CD8+ tumor infiltrating lymphocytes that recognized 1–3 neo-epitopes from somatic mutations occurring in the respective cancers." (PMID 28100240, 2017). "Once APCs verify the tumor antigen as foreign via their interaction with CD4+ and CD8+ T cells, the APCs signal for the proliferation of various T cell subtypes that also recognize the tumor antigen." (PMID 28434399, 2017). "The effect of CD4+ TILs on OS was related to sample size, sex, HBV infection, Child-Pugh score, TNM-stage, and tumor number." (PMID 28790445, 2017). "The immunoregulatory tryptophan-metabolizing enzymes indoleamin-2,3-dioxygenase (IDO) 1 and 2, are known to induce CD4+CD25+Foxp3+ regulatory T cells (Treg), which is a key player of suppressing anti-tumor immune responses." (PMID 29283429, 2017). "The decreased number of Treg cells and MDSCs in spleen of TSA-treated mice, compared to the vehicle-treated group could be because of the decreased number of total splenic CD4+ T cells associated with reduced tumor size, rather than the direct inhibitory effects of TSA on Treg cells and MDSCs." (PMID 28489607, 2017). "In the tumor bed of patients with hepatocellular carcinoma, a FOXP3+CD3+CD4+CD56+ population with immunosuppressive function has been found (similar to regulatory T cells)." (PMID 28791027, 2017). "Screening of immune cells was performed for CD4+ T cells, CD8+ T cells, B cells, dendritic cells and macrophages in splenocytes from tumor bearing mice by flow cytometry." (PMID 28903394, 2017). "In a mouse model, androgen ablation induced a transient increase of CD4+ T cells and CD8+ T cells in residual tumor." (PMID 28292326, 2017). "Immune function after tumor therapy was measured by continuous laboratory data as follows: CD3+, CD4+, CD8+, CD4+/CD8+ and Natural Killer cell (NK)." (PMID 28659623, 2017).
tumor (continued). "Among adaptive immune cells, Th2 cells, CD4+ T helper cells expressing Type 2 cytokines [e.g. interleukin (IL) 4, IL10], have been shown to promote tumor progression via activation of humoral immunity and inflammation." (PMID 28883015, 2017). "Therapeutic vaccination with VSV-E7 led to reduced TC-1 tumor volumes, and VSV-hDCT generated antigen-specific CD4 T cell responses in addition to CD8 T cells in murine melanoma." (PMID 28751892, 2017). "To identify immune cells that are important for reducing BPTF KD tumor growth, we repeated our tumor studies in mice depleted of NK cells, CD8+ T cells, or CD4+ T cells by monoclonal antibody (mAb) treatments." (PMID 28969075, 2017). "CD4+ and CD8+ T-cells, and NK cells were decreased in tumour bearing lungs of 5-LO knockout mice compared to wild-type while myeloid cell frequencies remained unchanged." (PMID 28125014, 2017). "Flow cytometry analysis of tumors revealed that percentages of tumor-infiltrating CD8+ and CD4+ T cells were higher in right flank tumors of mice treated with the combined treatment (mCelyvir-ICOVIR5)." (PMID 28525366, 2017). "By this means, Tregs are able to inhibit the proliferation of CD4+/CD8+ T cells and then suppress anti-tumor immune responds." (PMID 28978159, 2017). "We measured the number of tumor-specific CD8+ T lymphocytes and Foxp3+CD4+CD25+ Treg cells in tumor-bearing db/db mice." (PMID 28496193, 2017). "Ti-Treg and Ti-Teff cells are the main subsets of CD4+CCR4+ T cells, and they always are recruited into the tumor microenvironment via the CCL2/CCR4 axis." (PMID 29312296, 2017). "Combinatory therapy also heightened the potential of CD4+ T cells to produce IFN-γ and cooperatively eliminated myeloid derived suppressor cells (MDSCs) in tumor infiltrates." (PMID 26625316, 2016). "Regulatory T cells with a CD4+ CD25+ phenotype comprise about 5% to 10% of peripheral T cells and play a role in tumor immunology." (PMID 27540476, 2016). "We found that the combination of PD-1 blocking and CD137 agonism was most effective in enhancing the anti-tumor effect of SBRT, which was dependent on both CD4 and CD8 T cells." (PMID 27160390, 2016). "These facts suggested that CD4+ and CD8+ effector T cells were important participants in the antitumor immunity triggered by IL-21 and IL-7 co-expressing tumor cell vaccine, while NK cells are dispensable in such a process." (PMID 27571893, 2016). "As a comparison, deletion of both CD4+ and CD8+ T cells (GK1.5+2.43) ablated both improved mouse survival and suppressed tumour growth by combination therapy, pointing to critical roles of CD4+ and CD8+ T cells in this process." (PMID 27498556, 2016). "Activation of CD4+ T cells via MHC II presentation, with stimulation of B cells and resulting ADCC against tumor cells, is a possibility that should also be entertained." (PMID 27462315, 2016). "The frequency of CD4 + Foxp3+ regulatory T cells and myeloid-derived suppressor cells (MDSC) was lower in tumor samples from T-VEC- treated patients compared with tumor from non-treated melanoma patients." (PMID 27660707, 2016). "Among lymphocytes, NK cells and circulating CD3+, CD4+, CD8+, and CD19+ T lymphocytes are important in anti-tumor immunity." (PMID 27029063, 2016). "Because previous studies have revealed that tumor-derived TGF-β1 mediates the conversion of CD4+Foxp3+ Tregs, we measured the percentage of CD4+CD25+Foxp3+ Tregs and CD103+CD4+Foxp3+ cells in lymphocytes from the spleens and lungs of tumor-bearing mice." (PMID 27036297, 2016). "Infiltration of the tumor by cytotoxic CD8+ T-cells and memory CD4+ CD45RO+ cells proved to have prognostic discriminatory power, leading to a novel scoring system strongly correlated with the clinical outcome." (PMID 27689405, 2016). "In HIF-knock down mice an increased frequency and activation of CD4+ and CD8+ T cells was found, which produced higher levels of IFN-γ thereby enhancing anti-tumor responses." (PMID 27044404, 2016).
tumor (continued). "Results showed that only the CD4−CD8− thymocytes had enhanced Sca1 expression at 14 days post tumor challenge, but all four stages of thymocytes (CD4−CD8−, CD4+CD8+, CD4−CD8+, and CD4+CD8−) had drastically enhanced Sca1 expression at 21 days post challenge." (PMID 27277682, 2016). "IFN-γ ELISPOT assay showed that there were very few IFN-γ producing tumor-specific cells (mainly CD8+ T cells, CD4+ T cells and NK cells) in control mice treated with PBS saline." (PMID 26956047, 2016). "Using a mouse tumor model, several groups have reported that BCG-mediated antitumor activity requires a functional immune system, including CD4+ and CD8+ T lymphocytes." (PMID 27237631, 2016). "Regulatory T cells (Tregs, CD4+CD25+FoxP3+) also stimulate immune tolerance and facilitate tumor progression." (PMID 26862849, 2016). "EGFR875-889-specific CD4 T cells can be detected in the peripheral blood of HNSCC patients, and was shown to react against tumor cells expressing EGFR as well as other ErbB/HER family members (HER-2, HER-3) and c-kit, which have homologous peptide sequences." (PMID 27833557, 2016). "We predicted that the up-regulation of GITR on Tregs would result in disproportionate depletion of Tregs relative to CD4+ and CD8+ T cells after treatment with the anti-GITR IgG 2a (anti-GITR (2a)) mAb, as has been observed in flank tumor models." (PMID 27190629, 2016). "Fourteen patients with the PD‐1 expression were weakly positive in tumor microenvironment, meanwhile the median percentage and MFI of PD‐1 on CD4+ T cells were 17.28% (range: 3.25–46.45%) and 398.5 (range: 244–1590)." (PMID 27709793, 2016). "In summary, our study identified the elevated Tim‐3 on CD4+ T and CD8+ T cells from peripheral blood in OS patients, high Tim‐3 levels were positively correlated with tumor stages, metastasis, pathological tumor fracture, as well as poor prognosis." (PMID 27516959, 2016). "Despite similar methods of activation and similar ratios of CD4 to CD8 T cells, we observed almost a ten-fold difference in TNF-α, IL-6 and IFN-γ released from F9 T cells compared to F38 T cells in response to tumor cells 24JKERB." (PMID 27153556, 2016). "The number of tumor-infiltrating CD3+, CD4+, and CD8+ positive cells was dichotomized (CD3+ with a cutoff value of 150; CD8+ and CD4+ with a cutoff value of 100) and compared between HPV-positive and HPV-negative tumors." (PMID 26993499, 2016). "In vaccinated patients with VIN, infiltration of both CD4 and CD8 T cells into tumor sites was shown to correlate with tumor clearance." (PMID 27660710, 2016). "Consistent with flow cytometry data, the numbers of IFN-γ- and TNF-α-producing CD4 and CD8 T cells in spleen and tumor drLN were significantly increased by ascophyllan treatment." (PMID 27008707, 2016). "This resulted in a marked increase in the ratio of both CD4+ and CD8+ ICOS+ Teff to ICOS+ Tregs in the tumor/lungs and periphery in mice receiving MVA-BN-HER2 treatment compared to control mice." (PMID 26961085, 2016). "While wild-type mice showed similar (80%) protection effects to previous experiments in this study, antitumor immunity was severely compromised in both CD4 KO and CD8 KO mice, with tumor-free rate dropped sharply to 0% and 10%, respectively." (PMID 27571893, 2016). "The correlation between PD‐1 expression on CD4+ T cells of DLBCL patients and PD‐1 expression in tumor microenvironment is unclear." (PMID 27709793, 2016). "Protein expression of tumor-infiltrating lymphocytes (TILs) (CD3, CD4, and CD8) and granzyme inhibitors was analyzed in 262 OPSCCs by immunohistochemistry (IHC)." (PMID 26993499, 2016). "Reexpression of Cxcl14 increases natural killer, CD4+ T, and CD8+ T cells in tumor-draining lymph nodes in vivo." (PMID 27143385, 2016). "Immediately after tumor inoculation, the host mice were transplanted with 2×106 TCD-BM cells alone or combined with WT or GzmB−/− CD4+CD25− Tcon cells isolated from C57BL/6 (H-2b) donor mice." (PMID 27774524, 2016).
tumor (continued). "Our study demonstrated infiltration by both CD4+and CD8+T cells, with a predominance in the peritumoural stroma compared with tumour cell nests." (PMID 27777963, 2016). "Despite a similarity in their cytokine profile, CD4 Th1-like cells and CD8+ CTL exhibited different abilities to control tumor growth." (PMID 27588200, 2016). "Since the number and surface marker expression of cells in the tumor microenvironment were measured in this study, we used EMD to quantify changes in the balance between critical immune cell types (CD4, CD8, CD25 cells, etc.)in response to the radiotherapy." (PMID 27008164, 2016). "These DCs showed higher ability to activate antigen-specific CD4+ and CD8+ T cells, and to specifically induce tumor cell apoptosis." (PMID 27203391, 2016). "T cell proliferation was determined by analyzing Ki67 expression on tumor infiltrating CD8 and CD4 T cells." (PMID 27825115, 2016). "In accordance with the findings from the mRNA sequencing data, TIM-3, LAG-3 and CTLA-4 were expressed at higher levels in both CD4 and CD8 T cells from PD-1 resistant as compared with untreated EGFR TL tumours by flow cytometry analysis." (PMID 26883990, 2016). "Eradication of tumors depended upon a natural CD4+ and CD8+ T-cell presence in all our screening models, as administration of depleting anti-CD4/CD8 mAbs prevented CY+TLRa-mediated durable tumor rejection." (PMID 27341020, 2016). "Second, in order to quantitate the infiltration of CD19+ B cells and CD4+, CD8+ T cells we performed flow cytometric stainings on single tumour cell suspensions." (PMID 27427766, 2016). "Remarkably, when cocultured with splenocytes in vitro, GMPs stimulated a significant proportion of CD4 T cells to become Foxp3+CD25+ cells, and a higher level of induction was detected with cells from tumor-bearing mice (T-GMP) than those from normal mice." (PMID 26979287, 2016). "IFN-γ can be produced by NK cells, CD4+ or CD8+ T cells, and it is one of the major cytokines that have anti-tumor effects." (PMID 27835902, 2016). "It has been documented that tumor cells can induce Tregs in the tumor microenvironment by secreting soluble factors such as TGF-beta, VEGF and GM-CSF, which convert tissue infiltrating CD4+ T cells to Foxp3+ Treg." (PMID 27793053, 2016). "CSF2, which stimulates intra-tumoral dendritic cell expansion and induces significant CD4+ and CD8+ T cell anti-tumor immune responses was the top uniquely activated UPR (most significant UPR, based on p-value of overlap) in CPA-treated GL261 tumors." (PMID 27515027, 2016). "As elucidated previously, CD4+ and CD8+ T cells take center stage in bolstering the antitumor immunity elicited by IL-21 and IL-7 co-expressing tumor cell vaccine." (PMID 27571893, 2016). "In this study, we observed that radiation induced a dramatic increase in both CD4 and CD8 T cells in the tumor microenvironment." (PMID 27014915, 2016). "Endogenous as well as adoptively transferred CD4+ and CD8+ syngeneic T-cells have been employed to induce rejection in multiple tumor models." (PMID 27341020, 2016). "Further we show that the frequency of cytokine producing (IFN-γ) CD8+ and CD4+ T cells detected in the spleen was higher in Gel + OVA vaccinated mice than others, implying an IFNγ-mediated anti-tumour effect." (PMID 27756214, 2016). "However, the observation that IL-12-mediated tumor rejection operated in IFN-γ−, IFN-γR−, or perforin-deficient mice suggests that in this model NKp46+LTi do not contribute to the antitumor activity of other innate (NK) or adaptive (CD4+ and CD8+ T) cells in the TME." (PMID 27882334, 2016). "Our results showed that both CD8+ and CD4+ TILs co-expressed inhibitory receptors, PD-1 and LAG-3, and dual blockade of PD-1 and LAG-3 significantly suppressed the tumor growth of SCCs." (PMID 27835902, 2016).
tumor (continued). "Neither ZA nor NZ, alone and in combination with doxorubicin, modified the amount of intra-tumor CD19+, CD4+ or CD8+ cells, suggesting that they did not affect the amount of B- and T-lymphocytes infiltrating the tumor bulk." (PMID 26980746, 2016). "There was a higher CD3+ (p = 0.007), CD4+ (p = 0.025) and CD8+ count (p = 0.002) in the tumour of patients whose tumour nodal status was downstaged at pathological evaluation after NAC." (PMID 27020682, 2016). "Utilizing a therapeutic vaccination protocol as outlined, total CD4+ and CD8+ TILs were harvested 1 week after the second vaccination, counted by flow cytometry, and normalized by tumor size." (PMID 28018602, 2016). "Th1 cells, a subset of CD4+ T cells, constitutively express IFN-γ and TNF-α, and play a role in priming tumor-specific CTLs through the release of soluble IL-2 in the proximity of CTLs." (PMID 26795730, 2016). "Many tumor cells increase PD-L1 expression in response to local factors such as Interferon-γ (IFN-γ) released from CD4 helper, activated CD8+ T cells or NK cells in the tumor microenvironment." (PMID 26943572, 2016). "Both CD4 and CD8 T cells contribute to this T cell anti-tumor effect, and latent as well as lytic viral antigens are targeted." (PMID 27186886, 2016). "Antigen-specific CD4+ and CD8+ T cell responses against autologous tumor cells induced by allogeneic DC-tumor FCs are dependent on HLA type." (PMID 27240347, 2016). "One strategy to achieve this is tumor delivery of stimulator of interferon genes (STING) agonists, which have been shown in mouse models of glioma to promote infiltration by CD4 and CD8 T cells and prolong survival." (PMID 28003994, 2016). "Immunization of HLA-DR4 transgenic mice revealed that even in the presence of tumor, SCIB1 still generates high frequency and avidity CD8 and CD4 T cell responses." (PMID 27825115, 2016). "Although successes have been achieved with ACT products containing merely tumor-directed CD8+ T cells, there are indications that CD4+ T cells can help or can do the job." (PMID 27619514, 2016). "The expression of these two adhesion molecules then allowed the infiltration of CD4+ and CD8+, which mediate the tumor suppression." (PMID 27882334, 2016). "Tumour infiltrating lymphocytes (TILs: CD3+, CD4+, CD8+ and FOXp3+) were assessed by immunohistochemistry using tissue microarrays in a contemporary and homogeneous cohort of OAC patients (n = 128) undergoing curative treatment." (PMID 27020682, 2016). "Higher Treg levels in tumour tissues indicated a worse prognosis, and the FOXP3+ Tregs/CD4+ T cells ratio was an independent prognostic factor for OS." (PMID 27725696, 2016). "The tumor samples showed a higher prevalence of cells with memory phenotype CD4+CD45RO+, a higher prevalence of CD4+versus CD8+ T cells (CD4 > CD8), and a higher prevalence of Th1 versus Th17 phenotype, with a reduced presence of NK cells in TT." (PMID 27689405, 2016). "The decreases in number of CD4+ and CD8+ tumor-infiltrating lymphocytes (TILs) develop along the tumor advancement, indicating lower anti-tumor response." (PMID 26862849, 2016). "Depletion of either CD4+ (GK1.5) or CD8+ (2.43) T cells abolished mouse survival induced by combination therapy, although tumour growth was still delayed." (PMID 27498556, 2016). "After inoculation, allogeneic tumor cells, much like the cell in transplanted allogeneic organs, are recognized by both of CD8+ T cells and CD4+ T cells." (PMID 27448968, 2016). "In GBM, Tregs suppress CD4+ and CD8+ T-cell activation and are considered a major contributor to tumor progression." (PMID 26967393, 2016). "Positivity for CD4 and CD8 of tumor cells was found in 14.0% (6/43) and 2.4% (1/41) of the tested cases, respectively, but none expressed both antigens." (PMID 27564014, 2016).